INS (insulin)
Diseases named in the same sentence as INS in open-access papers (continued):
Sharing a sentence is not in itself a finding about the gene and the disease.
type 2 diabetes (continued). "Accordingly, insulin production requirements become greater, and the acquired resistance raises circulating glucose levels, increasing the risk of developing type 2 diabetes mellitus (T2DM)." (PMID 32752277, 2020). "The metabolic features of PCOS are defects in insulin action and β-cell function, which lead to an increased risk of glucose intolerance and type 2 diabetes." (PMID 32326591, 2020). "Methylation in CpG sites of the PPARGC1A gene (encoding PGC1-α) has been associated with adiposity, insulin secretion/sensitivity indexes and type 2 diabetes." (PMID 32933059, 2020). "It is well known that insulin resistance in target tissues and a deficiency in insulin secretion from pancreatic β-cells are the main characteristics of type 2 diabetes." (PMID 32927596, 2020). "Because postprandial hyperinsulinemia related to postprandial hyperglycemia is implicated in the etiology of type 2 diabetes complications, it is important to investigate how low GI/GL affect insulin sensitivity." (PMID 32471238, 2020). "ABCG1 CpG sites associated with type 2 diabetes, fasting glucose and fasting insulin in participants from the FHS and WHI studies." (PMID 32612641, 2020). "Aging is a well-known risk factor for type 2 diabetes (T2D), causing a decrease in insulin production and sensitivity cells." (PMID 32775431, 2020). "High-circulating levels of free fatty acids are one of the important pathogenic factors contributing to reduced insulin sensitivity and islet dysfunction in type 2 diabetes." (PMID 32686763, 2020). "Since diminished insulin secretion can be observed in metabolically healthy groups with a high risk of future development of type 2 diabetes, it can be regarded as an independent pathogenetic factor in the development of type 2 diabetes." (PMID 32570905, 2020). "All this supports the positive correlations observed here between statin use and insulin levels as well as glucose levels, which result in an increased risk of type 2 diabetes." (PMID 32612641, 2020). "Clinically, two of the most common types are type 1 diabetes (T1D), and type 2 diabetes (T2D), which are associated with the destruction of insulin-producing pancreatic β-cells and relative insulin deficiency caused by dysregulation of β-cells, respectively." (PMID 32764399, 2020). "It seems more likely to be driven by a particular metabolic feature of type 2 diabetes itself, such as increased fasting insulin levels, or by an associated trait, such as higher adiposity, as demonstrated by MR studies." (PMID 32705315, 2020). "Pancreatic beta cell characteristics and insulin secretion are modulated by neuronal and hormonal inputs, and defects in beta cell function underpin the risk of type 2 diabetes." (PMID 32860984, 2020). "Type 2 diabetes is a progressive endocrine disease caused by a combination of failure of the β-cells of the pancreas to secrete enough insulin and the failure of the body to utilize insulin effectively." (PMID 33261162, 2020). "As early as in 1965, the World Health Organization (WHO) recognized two main groups in type 2 diabetes: insulin resistant and insulin deficient subjects." (PMID 32785111, 2020). "Deficiencies in β-cell insulin secretion result in the development of type 1 and type 2 diabetes, metabolic disorders characterized by high levels of blood glucose." (PMID 32150819, 2020). "Combining results from the first and second steps of MR, the causal effect of statins on type 2 diabetes, glucose, and insulin through cg06500161 methylation was calculated as 0.0177, 3.49E-3 and 0.0209, respectively." (PMID 32612641, 2020). "In the present study, FHD, instead of type 2 diabetes risk alleles, has been demonstrated to be associated with not only reduced birth weight but also decreased early-phase insulin secretion and increased glucose excursion in Japanese women aged 20 years." (PMID 33490284, 2020).
type 2 diabetes (continued). "Over 90% of patients with type 2 diabetes and failure of metformin reached their HbA1c goal with additional basal insulin at bedtime over several years in association with a reduction of bodyweight and without any event of severe hypoglycaemia." (PMID 32316649, 2020). "Type 2 diabetes and dysfunctional insulin signaling is associated with increased rates of proliferative diabetic retinopathy and macular edema in patients." (PMID 32432228, 2020). "Low IGF-1 levels have previously been linked with reduced insulin sensitivity, and with a higher risk of glucose intolerance and type 2 diabetes." (PMID 32655494, 2020). "In contrast, type 2 diabetes occurs by a resistance to insulin action or insulin deficiency (90% type 2 diabetes)." (PMID 33139638, 2020). "CpG cg06500161 methylation was validated as the causal factor with type 2 diabetes, glucose and insulin as the outcomes." (PMID 32612641, 2020). "To date, type 2 diabetes has been controlled through weight loss, healthy eating, regular exercise, diabetes medication or insulin therapy, and blood sugar monitoring." (PMID 34026300, 2020). "Type 2 diabetics need to enhance their body’s sensitivity to insulin which can be accomplished by exercise, diet, insulin therapy and weight loss." (PMID 32106464, 2020). "Munc18 proteins are essential regulators of SNARE-mediated exocytosis and reduction in Munc18/SNARE complex has been implicated in the loss of first phase of insulin secretion in type 2 diabetes (Gaisano, 2014)." (PMID 33088259, 2020). "In conclusion, elevated WBC levels accompanied by an increased GLR and a decreased PLR were associated with the risk of type 2 diabetes based on increased insulin and HOMA-IR levels and decreased adiponectin levels." (PMID 32346379, 2020). "Meanwhile, HFD-induced obesity is characterized by an increased risk of type 2 diabetes with increased serum insulin levels." (PMID 33138053, 2020). "Although insulin administration can treat type-2 diabetes, its chronic use increases the risk of cancer." (PMID 32392536, 2020). "The inherent reasons for deficient insulin secretion in type 2 diabetes and for autoimmunity against insulin granule components are, however, yet to be discovered." (PMID 32894308, 2020). "In patients with type-I or type-II diabetes, TI was associated with less weight gain compared with subcutaneous insulin and oral pharmacotherapy (1 versus 1.64 kg)." (PMID 32785196, 2020). "Our results showed that the Bacteroides enterotype was an independent risk factor for type 2 diabetes, which was due to increased levels of lipopolysaccharide causing decreased insulin sensitivity.Bacteroides and Prevotella enterotype." (PMID 32064276, 2020). "In this study of young Mexican-Americans with an increased predisposition for type 2 diabetes, we report the effects of eight weeks of combined aerobic and resistance exercise training on insulin sensitivity and metabolic flexibility." (PMID 32231642, 2020). "This study reveals that peripheral neuropathy, defined by a NDS score≥6, in type 2 diabetic patients is significantly associated with height, insulin treatment, retinopathy treated with laser, total cholesterol and, particularly to dp-ucMGP plasma levels." (PMID 32092076, 2020). "Factoring in islet hub SNPs in a polygenic risk score improved identification of individuals with risk of type 2 diabetes, possibly acting through islet gene regulation and insulin secretion pathways." (PMID 32797243, 2020). "In our previous study, we found that 1,5-anhydroglucitol was not only correlated with insulin sensitivity and secretion but also closely associated with early-phase insulin secretion in Chinese patients with type 2 diabetes." (PMID 32775460, 2020). "Obese patients with Type-2 diabetes can benefit from weight loss, with abnormal blood glucose and lipid metabolism improved, insulin resistance relieved, and insulin sensitivity increased." (PMID 33235568, 2020).
type 2 diabetes (continued). "This is consistent with studies showing that individuals with type-2 diabetes who are treated with insulin have an increased risk for malignancies, including breast cancer." (PMID 32153503, 2020). "It is worth noting that ongoing clinical trials are documenting a significant improvement of glycaemic control in both Type 1 and Type 2 diabetes, in conjunction with smaller postprandial plasma glucose excursions, lower insulin requirements, and weight loss." (PMID 32225082, 2020). "The development of obesity involved alterations in many biochemical processes and a pro-inflammatory state in insulin-sensitive tissues, leading to an increased risk of developing cardiovascular disease, type 2 diabetes, and cancer." (PMID 33348802, 2020). "Another clinical trial that investigated the effect of 6 months CR in patients with type 2 diabetes with abdominal obesity, showed that the CR improved glomerular hyperfiltration, decreased cardiovascular risk factors and improved insulin sensitivity." (PMID 32235611, 2020). "Infection with parasitic helminths has been reported to improve insulin sensitivity and glucose homeostasis, lowering the risk for type 2 diabetes." (PMID 32614822, 2020). "Exercise training increased whole-body insulin-mediated glucose disposal in obese type 2 diabetic patients, and these changes are associated with increased GLUT4 protein content in skeletal muscle." (PMID 32591906, 2020). "Postprandial glycaemia together with dietary patterns that induce excessive insulin secretion have been associated with weight gain and a higher risk of developing type 2 diabetes." (PMID 32366255, 2020). "We found that DNA methylation at one CpG, cg1680945 (MDN1), which was associated with adult type 2 diabetes in a previous study, was also associated with maternal early-pregnancy insulin concentrations." (PMID 32894192, 2020). "Most of these type 2 diabetes susceptibility genes were associated with the expression and/or function in beta cells and changed insulin secretion." (PMID 33353041, 2020). "Previously, insulin signaling and type 2 diabetes have been found to be associated with changes in DNA methylation." (PMID 33298174, 2020). "Regular consumption of low glycaemic index (GI) foods, minimizing spikes in blood sugar and insulin levels, is associated with a reduced risk for developing type 2 diabetes and heart disease, and assists in weight management." (PMID 32366255, 2020). "Impaired liver and skeletal muscle insulin sensitivity are considered major risk factors for the development of type 2 diabetes." (PMID 31690989, 2020). "It has been demonstrated that transcription factor 7-like 2 (TCF7L2)-rs7903146 polymorphism is associated with increased risk of type 2 diabetes and the response of insulin." (PMID 33126534, 2020). "We found that early age at PHV was associated with increased risk of insulin-treated type 2 diabetes (OR 1.25 per year decrease in age at PHV, 95% CI 1.17, 1.33)." (PMID 32201902, 2020). "Accumulation of N-acyl taurines has been implicated to increase insulin secretion, leading to β cell dysfunction in type 2 diabetes in mice." (PMID 32163448, 2020). "Loss of Sac2 results in impaired insulin secretion, and Sac2 mRNA levels are reduced in type 2 diabetes." (PMID 31533953, 2019). "The majority of studies linking KCNQ1 with insulin secretion defects and type 2 diabetes risk have focused upon patients with type 2 diabetes." (PMID 30641161, 2019). "A decline in insulin sensitivity is an early sign of susceptibility to type 2 diabetes, typically manifested as elevated levels of fasting insulin." (PMID 31779625, 2019). "Prolonged activation of inflammation is an important component of type 1 and type 2 diabetes progression, and its association with insulin secretion and apoptosis in beta cells has been well established." (PMID 30974824, 2019).
type 2 diabetes (continued). "These pathways, in turn, impede insulin signaling and glucose transport activity, leading to insulin resistance which is associated with metabolic syndrome, obesity, type 2 diabetes (T2D) and diabetic vascular complications." (PMID 31068904, 2019). "The progression of type 2 diabetes is associated with autophagy through insulin secretion deficiency and the development of insulin resistance." (PMID 30744021, 2019). "Resistance to insulin in obese patient is well documented and is linked to type 2-diabetes, hepatic steatosis and other components of metabolic syndrome." (PMID 30616512, 2019). "Despite having a high accumulation of body fat, MHO individuals display lower levels of C-reactive protein, higher adiponectin concentrations, higher insulin sensitivity, and a lower risk of type 2 diabetes." (PMID 31789604, 2019). "SHIP2 is an important regulator of energy metabolism, such as its negative regulation of insulin signaling and its correlation with susceptibility to type 2 diabetes." (PMID 31357665, 2019). "In particular the stimulation of beta cell function and inhibition of glucagon secretion were important, since insufficient insulin secretion and hypersecretion of glucagon were at that time emerging as the key defects underlying type 2 diabetes." (PMID 31275243, 2019). "Glucose,insulin, glycosylated hemoglobin A1c and insulin resistance increased inparallel to the increased risk for type 2 diabetes, although lipids did notincrease." (PMID 31340346, 2019). "For AD, an insulin signaling pathway disorder is one of the causes of its pathogenesis; whilst Aβ aggregation and oxidative stress are also factors that lead to type II diabetes." (PMID 31064071, 2019). "The dedifferentiation causes the loss of functional β-cell mass with ultimately defective insulin secretion in type 2 diabetes." (PMID 30450940, 2019). "In youth-onset type 2 diabetes, the most important risk factor for glomerular hyperfiltration is insulin resistance." (PMID 30872684, 2019). "The significant changes in the plasma profile of omentin-1, NGAL and CTRP3 during insulin therapy suggest their potential diagnostic utility in monitoring metabolic changes associated with the introduction of insulin treatment in type 2 diabetic patients." (PMID 31195747, 2019). "IR is characterized by a decrease in the effect of insulin despite an increase in insulin concentration, and is associated with type 2 diabetes, hypertension, atherosclerosis, NAFLD and so on." (PMID 31661889, 2019). "Type 2 diabetes is associated with a number of metabolic defects resulting from decreased insulin sensitivity, many of which likely take part in the development and progression of the disease." (PMID 30837889, 2019). "In type 2 diabetes, defects in insulin granule docking at the plasma membrane result in reduced numbers of fusion-competent granules and contribute to the impaired insulin secretion associated with this disease." (PMID 31533953, 2019). "The SLC30A8 genotype appears to impact insulin production and rare protective loss-of-function mutations in this gene can increase insulin secretory capacity and reduce type 2 diabetes risk considerably." (PMID 31444530, 2019). "A 2017 study of obese, nondiabetic children aged 8–15 years in the United States found that proximity to air with nitrogen dioxide and particulate matter contaminants decreased insulin sensitivity and increased Type II diabetes risk at early adulthood." (PMID 31181712, 2019). "Further work is needed to confirm the association between KCNQ1 SNPs and insulin sensitivity, and to test any association between genotype and overt type 2 diabetes in other study populations." (PMID 30641161, 2019). "It is characterized by altered glucose levels in the blood, divided into two main types: diabetes mellitus type I, due to a deficiency in insulin production, and diabetes mellitus type II, due to resistance to insulin action in the body." (PMID 30805360, 2019).
type 2 diabetes (continued). "Pancreatic beta cells secrete insulin to maintain glucose homeostasis, and beta cell failure is a hallmark of type 2 diabetes." (PMID 30334081, 2019). "Genome-wide association studies have revealed the correlation of single nucleotide polymorphisms of type 2 diabetes with defect in secretion of insulin, which corresponds to abnormality in pancreatic islet cells." (PMID 32010189, 2019). "Impairment of insulin signalling in skeletal muscle, liver and adipose tissues due to the progressive insulin resistance is the main cause of type 2 diabetes." (PMID 31060468, 2019). "There was no strong statistical evidence that chronotype was causally associated with BMI, fasting insulin or risk of type 2 diabetes (IVW P > 0.1), as previously reported." (PMID 30696823, 2019). "Despite not reaching genome-wide significance, the association with rs12277475 (p = 2.0 × 10−7) near the INS (insulin) gene was of interest given previous reports of a significant African-American type 2 diabetes association signal at rs3842770, 28 kb away." (PMID 31049640, 2019). "A cross-sectional study (aged 65+in Northern China) revealed risk factors for MCI to be age at onset and biomarkers of type 2 diabetes severity such as fasting plasma glucose, glycosylated hemoglobin, and immunoreactive insulin." (PMID 31709214, 2019). "Our findings indicate that the concept of insulin resistance underlying metabolic diseases such as type 2 diabetes can be extended to the field of skin physiology." (PMID 31581253, 2019). "Fasting plasma glucose (FPG), glycosylated hemoglobin (HbA1c) and immunoreactive insulin (IRI) were associated with increasing risk for MCI with Type 2 diabetes (T2DM)." (PMID 31709214, 2019). "Although less studied in humans, agonists of α2AAR can prevent excess insulin release and variants of α2AAR are apparently associated with type 2 diabetes." (PMID 31354618, 2019). "In obese and type 2 diabetics patients, up-regulation of IL-6 levels were associated with elevated blood sugar levels, low sugar tolerance and decreased sensitivity to insulin." (PMID 30463907, 2019). "To investigate this in more detail, we used a genetic instrument for ‘favourable adiposity’, where alleles associated with higher BMI are associated with lower risk of type 2 diabetes, and lower insulin levels." (PMID 30423117, 2019). "The loss or dysfunction of insulin-producing β-cells, in patients with type 1 and type 2 diabetes respectively, put these cells at the center of the disease initiation and progression." (PMID 31671683, 2019). "Type 2 diabetes mellitus (T2D), characterized by hyperglycemia, results from dysfunctional carbohydrate metabolism that is caused by a relative deficiency of insulin." (PMID 30929133, 2019). "Hyperglycaemia and type 2 diabetes (T2D) are associated with impaired insulin secretion and/or insulin action." (PMID 31208038, 2019). "Type 2 diabetes is caused by impaired β-cells function and capacity to secrete sufficient insulin, coupled with a decline in target tissue sensitivity to insulin (insulin resistance)." (PMID 31665087, 2019). "Accordingly, NINJ1 is associated with insulin insensitivity and type 2 diabetes incidence in African Americans61." (PMID 30700695, 2019). "Pancreatic atrophy was associated with the loss of insulin secretory capacity in patients with type 2 diabetes." (PMID 31467928, 2019). "First, because human insulin remains widely used for the treatment of hyperglycemia in either type 1 or type 2 diabetes patients, its potential risk of lung cancer warrants intensive investigation and immediate confirmation." (PMID 31354621, 2019). "Type-1 diabetes is characterized by autoimmune-mediated pancreatic β-cell and results in the deficiency of insulin, whereas type-2 diabetes is peripheral insulin resistance." (PMID 31514311, 2019).